EGR1 (early growth response 1)
Diseases named in the same sentence as EGR1 in open-access papers (continued):
Sharing a sentence is not in itself a finding about the gene and the disease.
myeloid leukemia (2 papers, 2009 to 2017). A clonal proliferation of myeloid cells and their precursors in the bone marrow, peripheral blood, and spleen. "It has also been shown that Ezh2 directly regulates Egr1 in hematopoiesis, and that deletion of Ezh2 and the reactivation of genes repressed by it, including Egr1, converted a high-grade myeloid leukemia to a less aggressive myeloid neoplasia (MPN)." (PMID 29050203, 2017). "Taken together, these data indicate that EGR-1 has an important role during monocyte differentiation in THP-1 cells as well as other myeloid leukemia cell lines and normal myeloblasts." (PMID 19374776, 2009). "Liebermann and colleagues reported that antisense oligomers for Egr-1 blocked macrophage differentiation in myeloid leukemia cell lines and normal myeloblasts, and ectopic expression of Egr-1 in cell lines and primary bone marrow resulted in activation of the macrophage differentiation program." (PMID 19374776, 2009).
myeloproliferative disorder (2 papers, 2011 to 2017). A clonal hematopoietic stem cell disorder, characterized by proliferation in the bone marrow of one or more of the myeloid (i.e., granulocytic, erythroid, megakaryocytic, and mast cell) lineages. "ENU-treated Egr1+/− and Egr1−/− mice developed a myeloproliferative disorder with ineffective erythropoiesis (MPD) at a high incidence." (PMID 21713073, 2011). "Interestingly, haploinsufficiency of EGR1 increased the frequency of myeloproliferative disorder (MPD) and decreased latency in mice treated with a DNA alkylating agent-N-ethyl-nitrosourea (ENU), to induce secondary mutations." (PMID 28081176, 2017).
ovarian tumor (2 papers, 2021 to 2023). "Clinical studies reported that the depletion of EGR1 sensitizes the chemotherapy of cisplatin in ovarian tumors." (PMID 34497759, 2021). "EGR1 regulated miR-152 and ATG14, which then improved CDDP sensitivity in ovarian tumor cells." (PMID 37098542, 2023).
pancreatic adenocarcinoma (2 papers, 2018 to 2024). "Tumor-related activation of transcription factor Egr1 caused induction of genes encoding T-UCRs in pancreatic adenocarcinoma." (PMID 29928487, 2018). "Therefore, we focused on the role of EGR1 in pancreatic adenocarcinoma by observing the effects produced by silencing this gene in vitro and in vivo." (PMID 38408959, 2024). "In this study, we found that EGR1 expression is elevated in pancreatic adenocarcinoma." (PMID 38408959, 2024).
pancreatitis (2 papers, 2016). Inflammation of the pancreas. "EGR1 has been shown to be a stress response gene with increased expression in pancreatic acini following exposure to caerulein, an inducer of pancreatitis." (PMID 27363020, 2016). "AG1478-treated AGR2+/- heterozygotes with pancreatitis also exhibited significantly reduced nuclear EGR1 compared to AG1478-untreated heterozygotes, but MKI67 was not significantly affected." (PMID 27764193, 2016). "EGFR signaling during pancreatitis was significantly reduced by AG1478 as determined by cell surface phosphorylated EGFR, nuclear EGR1, and AREG expression." (PMID 27764193, 2016). "Although EGFR signaling and cell proliferation, as represented by nuclear EGR1 and MKI67, were significantly induced in AGR2+/- mice with pancreatitis on Day 1, the levels were 65% and 75% lower, respectively, than wild-type AGR2+/+ mice." (PMID 27764193, 2016).
parasite infection (2 papers, 2012 to 2023). "Egr1 is expressed in response to a wide range of cellular stresses, including bacterial and parasitic infection, and its product contributes to the regulation of hundreds of genes." (PMID 23248776, 2012).
pneumonia (2 papers, 2010 to 2022). An acute, acute and chronic, or chronic inflammation focally or diffusely affecting the lung parenchyma, caused by an infection in one or both of the lungs (by bacteria, viruses, fungi, or mycoplasma.). "EGR1 expression was also elevated in the pneumonia group, which inhibits pro-inflammatory genes in developing and mature macrophages." (PMID 36119044, 2022). "EGR1 and IL-6 mRNA expression correlated with anastomotic leak and pneumonia at POD 3 by regression analysis (p = 0.021)." (PMID 20969744, 2010).
polycystic kidney disease (2 papers, 2010 to 2025). A usually autosomal dominant and less frequently autosomal recessive genetic disorder characterized by the presence of numerous cysts in the kidneys leading to end-stage renal failure. "Two genes, EGR1 (up-regulated) and polycystic kidney disease 1-like (down-regulated), were commonly regulated in both Ishikawa H and Hec50co cells in response to EGF at 12 h." (PMID 20579378, 2010).
proliferative diabetic retinopathy (2 papers, 2021 to 2025). Advanced retinopathy due to diabetes mellitus characterized by the formation of new vessels in the retina. "An ocular vascular disease-related study demonstrated that EGR1 is expressed in vascular endothelial cells isolated from the active membranes of proliferative diabetic retinopathy (PDR) and proliferative vitreoretinopathy (PVR) patients." (PMID 34608841, 2021).
psychosis (2 papers, 2015 to 2016). "Thus, our data on EGR1 levels in blood are particularly interesting because they reveal a putative specific marker able to differentiate SCZ from other major psychosis patients." (PMID 25658856, 2015).
sarcopenia (2 papers, 2017 to 2022). Progressive decline in muscle mass due to aging which results in decreased functional capacity of muscles. "Therefore, the decreased expression of EGR1 in the elderly may contribute to reduced muscle function in sarcopenia." (PMID 35271662, 2022).
thrombosis (2 papers, 2020 to 2021). "Meanwhile, a relevant study has shown that high expression of Egr1 was associated with thrombosis in human AAA." (PMID 32629426, 2020). "In venous thrombosis, hypoxia and inflammatory stimuli induced the coagulation cascade under low shear stress via the activation and regional release of relevant transcriptional factors [hypoxia-inducible factor 1 (HIF-1) and early growth response 1 (EGR-1)] and TFs." (PMID 34336810, 2021).
Tinnitus (2 papers, 2017 to 2024). Tinnitus is an auditory perception that can be described as the experience of sound, in the ear or in the head, in the absence of external acoustic stimulation. "Rats were treated with doses known to induce tinnitus in rats (300 mg/kg i.p. daily, for 3 days), and c-fos and Egr-1 protein expressions were analyzed using western blot and immunocytochemistry." (PMID 27174774, 2017). "The results of these alterations indicate that c-fos, EGR-1, and BDNF are probably involved in the regulation of neural excitability in response to cerebral venous congestion-related tinnitus." (PMID 38594782, 2024). "In this study, we aimed to investigate the activation of c-fos and Egr-1 in the DCN and IC in auditory pathways of rats subjected to a protocol of salicylate administration, which is effective in inducing tinnitus in rats (3 daily doses of 300 mg/kg)." (PMID 27174774, 2017).
Uterine leiomyoma (2 papers, 2016 to 2019). The presence of a leiomyoma of the uterus. "Early growth response gene 1 (Egr1) promotes the expression of AP-1; the induction of Egr1 in uterine leiomyoma cells led to a significant increase in the expression levels of Egr1, ATF3, Fos, and Jun." (PMID 31010998, 2019). "In response to smooth muscle injury, EGR1 may activate matrix remodeling genes and profibrotic genes such as TGF-β, PDGF, and Collagen 1 genes, which have all been suggested as etiological factors involved in the pathogenesis of human uterine leiomyomas." (PMID 27582276, 2016).
acute pancreatitis (1 paper, 2024). An acute inflammatory process that leads to necrosis of the pancreatic parenchyma. "In a study on acute pancreatitis, deficiency of Egr-1 was found to mitigate cerulein-induced inflammation and protect the pancreas by reducing cytotoxic and proinflammatory cytokines." (PMID 38233877, 2024).
alcoholic liver diseases (1 paper, 2019). A disorder caused by damage to the liver parenchyma due to alcohol consumption. "EGR-1 overexpression links to alcohol-induced liver disease and related to CCA may be used as a potential target for alcoholic liver disease diagnosis." (PMID 31795085, 2019).
allergic rhinitis (1 paper, 2024). Inflammation of the nasal mucous membranes caused by an IgE-mediated response to external allergens. "Furthermore, the MCODE plugin was employed to pinpoint 14 genes (Cyba, Nfkbia, Fos, Mpo, Il6, Il1b, Sele, Vcam1, F2, Tlr4, Alb, Egr1, Smad3, and Ptgs2) forming a primary cluster, potentially representing a crucial regulatory network for berberine in treating allergic rhinitis." (PMID 38796469, 2024).
amblyopia (1 paper, 2021). Decreased vision that results from abnormal visual development. "The appearance of this result provides strong proof for the association between Egr-1 and amblyopia." (PMID 34781927, 2021). "Monocular form deprivation amblyopia can lead to the decrease of Egr-1 protein and mRNA expression in visual cortex, and then promote the occurrence and development of amblyopia." (PMID 34781927, 2021). "Based on this method, the expression of Egr-1 in the visual cortex decreased significantly in amblyopia animal model." (PMID 34781927, 2021). "Immunohistochemistry and in situ hybridization were used to compare and analyze the expression of Egr-1 protein and mRNA in the visual cortex of 8-week-old amblyopia kittens and normal kittens." (PMID 34781927, 2021). "The present study compared the expression of early growth responsive gene-1 (Egr-1) in visual cortex between amblyopia kittens and normal kittens, and to explore the role of Egr-1 in the pathogenesis of amblyopia." (PMID 34781927, 2021). "Therefore, we examined changes in Egr-1 in the visual cortex in amblyopia to investigate the significance of this body in the pathogenesis of amblyopia and provide theoretical support for the occurrence and development of amblyopia." (PMID 34781927, 2021). "However, there has been no study on the correlation between the expression of Egr-1 and amblyopia." (PMID 34781927, 2021).
anaphylaxis (1 paper, 2024). An acute hypersensitivity reaction that occurs from exposure to an allergen. "This implies that Egr1 plays a role in allergic inflammations such as anaphylaxis." (PMID 38666929, 2024).
angioimmunoblastic T-cell lymphoma (1 paper, 2022). A mature T-cell non-Hodgkin lymphoma, characterized by systemic disease and a polymorphous infiltrate involving lymph nodes and extranodal sites. "In contrast, polyclonal T-cells had up-regulation of genes related to HTLV-1 infection (NFKBIA and EGR1), cytokine interaction (CCL4 and IL2RG), apoptosis, and inflammatory response, as well as genes down-regulated in angioimmunoblastic T-cell lymphoma (AILT)." (PMID 35464471, 2022).
astroglioma (1 paper, 2017). "Finally, the presence and mutual binding of RNA POL II and Egr-1 in the nuclei of C6 astroglioma cells were assessed by immunofluorescence and co-immunoprecipitation (co-IP)." (PMID 28187447, 2017). "The effects of Egr-1 overexpression on the binding of Egr-1 and RNA POL II to GDNF promoter II and GDNF transcription were examined by ChIP-PCR and real-time PCR in C6 astroglioma cells." (PMID 28187447, 2017).
atrial fibrillation (1 paper, 2025). A disorder characterized by an electrocardiographic finding of a supraventricular arrhythmia characterized by the replacement of consistent P waves by rapid oscillations or fibrillatory waves that vary in size, shape and timing and are accompanied by an irregular ventricular response. "ECG analysis revealed a high incidence of atrial fibrillation (AF), frequent AF episodes, and prolonged mean AF duration in circNAB1(+) mice following TAC and delivery of EGR1, Gadd45b, or Runx1, comparable to control vector delivered mice." (PMID 40145839, 2025).
Atrophy (1 paper, 2025). Any weakening or degeneration, especially through lack of use. "Ligustilide treatment reduced DSS-triggered weight loss, increased DAI scores, reduced spleen enlargement and thymic atrophy, increased colon length, restored colonic pathological structure, increased expressions of ZO-1 and Occludin, and decreased EGR1 downstream target protein ADAM17 expression." (PMID 40904624, 2025).
avian influenza (1 paper, 2022). Infection of domestic and wild fowl and other birds with influenza A virus. "After the analysis of DEGs and hub genes, a total of three genes, namely EGR1, JUN and FOS, were screened, which have been reported to have a major role in the resistance of chickens to avian influenza." (PMID 36557693, 2022).
bacterial meningitis (1 paper, 2024). Inflammation of the membranes surrounding the brain and spinal cord due to a bacterial infection. "However, the potential molecular regulatory mechanisms of Egr-1 in bacterial meningitis remain unclear." (PMID 38233877, 2024). "Our findings support an Egr-1-dependent mechanism of BBB disruption by meningitic E. coli, highlighting a promising therapeutic target for bacterial meningitis." (PMID 38233877, 2024).
bladder tumors (1 paper, 2009). "In some cases, tumor cells with nuclear Egr-1 immunolabelling were found to localize predominantly at the tumor front, i.e. at the border between the bladder tumor and the normal bladder stromal cells." (PMID 19878561, 2009). "By performing chromatin immunoprecipitation experiments with Egr-1 antibodies, it may be feasible to determine genes regulated by Egr-1 in invasive human bladder tumor specimens." (PMID 19878561, 2009). "Egr-1 is induced by epidermal growth factor (EGF) and has been shown to correlate to EGF receptor (EGFr) levels in bladder tumors." (PMID 19878561, 2009).
Cachexia (1 paper, 2012). Severe weight loss, wasting of muscle, loss of appetite, and general debility related to a chronic disease. "Comparison of tissue sections revealed a significantly stronger immunohistochemical signal of Egr-1 protein in the skeletal muscle tissue cells of patients with cachexia, as indicated by increased fluorescent staining." (PMID 22721276, 2012). "Furthermore, this report provides new insights into the inflammatory response involved in initiation and progression of cachexia by the activation of pro-inflammatory transcription factor Egr-1 and acute-phase response." (PMID 22721276, 2012). "The expression sites of Egr-1 protein were identified both in longitudinal and transverse sections of the skeletal muscle from patients either with or without cachexia by immunohistochemical staining with Egr-1 antibodies." (PMID 22721276, 2012).
carcinoid (1 paper, 2014). "We found increased expression of EGR1 in the NETs and that knockdown of EGR1 inhibited growth of the carcinoid cells." (PMID 25546138, 2014). "We found that knock down of EGR1 and G3BP1 inhibited the growth of carcinoid cell lines compared to controls." (PMID 25546138, 2014). "To characterize the biology of EGR1 and G3BP1 in NETs, we examined their importance for growth of carcinoid cell lines." (PMID 25546138, 2014). "Western blot analyses confirmed that the expression of the EGR1 and G3BP1 proteins were reduced after re-introduction of miR-129-5p to both carcinoid cell lines." (PMID 25546138, 2014).
cataract (1 paper, 2023). Partial or complete opacity of the crystalline lens of one or both eyes that decreases visual acuity and eventually results in blindness. "Compared with the ARC group, the levels of CTGF, FOS, CAV1, CYR61, ICAM1, EGR1, and NR4A1 in the anterior capsule of PACG patients with cataracts were upregulated, which was consistent with the sequencing data." (PMID 37131205, 2023).
Cerebral Aneurysms (1 paper, 2025). "This study shows that KP‐10 binding to Gpr54 inhibits Egr‐1 expression, thereby suppressing MMP‐9 and VEGF‐A, reducing macrophage infiltration and angiogenesis, and preventing cerebral aneurysm development." (PMID 40384564, 2025).
Cerebral ischemia (1 paper, 2020). Restriction of arterial blood supply to the brain associated with insufficient oxygenation to support the metabolic requirements of the tissue. "Egr1 was found to rapid activation in response to oxygen deprivation underlying ischemic stress and participated in the regulation of inflammation and neuronal damage and resulted in secondary brain damage after cerebral ischemia indicating a variety of downstream genes were activated." (PMID 33414894, 2020).
Chagas disease (1 paper, 2025). A parasitic infection caused by Trypanosoma cruzi. "The up- or down-regulation of these piRNAs, e.g., npiR_167, that targets the pro-fibrotic transcription factor EGR1, suggested that these molecules could serve as markers in Chagas disease." (PMID 41295584, 2025).
chronic gastritis (1 paper, 2018). Inflammation of the stomach that is chronic in nature. "Based on gene expression quantity, TFF1 and EGR1 can be introduced as the most critical genes related to chronic gastritis." (PMID 30425814, 2018).
co-infection (1 paper, 2012). "EGR1, KLF4, and GPR56 were selected in the case of HIV/HCV co-infection vs the HCV mono-infection." (PMID 23028845, 2012).
cocaine addiction (1 paper, 2023). "CTD showed that FOS and EGR1 could be biomarkers of cocaine addiction or play a role in addiction, and EGR1 could be a gene for a therapeutic target in the treatment of cocaine addiction." (PMID 37469839, 2023). "In summary, this study identified four key genes (FOS, IL6, EGR1, and JUN) that might be involved in cocaine addiction mechanisms and had potential roles as biomarkers and therapeutic targets for cocaine addiction." (PMID 37469839, 2023). "Four key genes (JUN, FOS, EGR1, and IL6) were identified and well validated using CTD database correlation analysis, text mining, independent dataset analysis, and enrichment analysis methods, and they might serve as biomarkers of cocaine addiction." (PMID 37469839, 2023).
congenital heart disease (1 paper, 2022). A heart disease that is present at birth. "In addition to these functions, EGR1 governed vascular remodeling in experimental PAH, and high EGR1 levels were detected in advanced vascular lesions of patients suffering from advanced-stage congenital heart disease-associated PAH." (PMID 35625405, 2022).
diffuse large B-cell lymphoma (1 paper, 2025). "Likewise, early growth response gene 1 (EGR1) is highly expressed in MCL and diffuse large B-cell lymphoma (DLBCL) cells progressing on ibrutinib and is partially responsible for the increased oxygen consumption rate." (PMID 41213958, 2025).
experimental autoimmune encephalomyelitis (1 paper, 2025). An autoimmune demyelinating disease of the central nervous system that is produced experimentally in animals by the injection of homogenized brain or spinal cord in Freund's adjuvant. "In this context, we demonstrated that the selective ablation of early growth response gene 1 (Egr-1) in CD4+ T cells exacerbated experimental autoimmune encephalomyelitis (EAE) in murine models." (PMID 40235598, 2025).
Fanconi anemia (1 paper, 2015). Fanconi anemia (FA) is a hereditary DNA repair disorder characterized by progressive pancytopenia with bone marrow failure, variable congenital malformations and predisposition to develop hematological or solid tumors. "We performed DRIP-qPCR in four human genes, APOE, RPL13A, EGR1 and BTBD19 in well-established cell lines derived from Fanconi Anemia patients." (PMID 26584049, 2015).
female infertility (1 paper, 2021). Diminished or absent ability of a female to achieve conception. "EGR1 positively regulates DMRT1 expression through promoter binding in Sertoli cells, but knock-out of this gene can also cause female infertility in mice." (PMID 33857129, 2021).